ITGB7 (integrin subunit beta 7)
Description:
Integrin ITGA4/ITGB7 (alpha-4/beta-7) (Peyer patches-specific homing receptor LPAM-1) is an adhesion molecule that mediates lymphocyte migration and homing to gut-associated lymphoid tissue (GALT) (Probable). Integrin ITGA4/ITGB7 interacts with the cell surface adhesion molecules MADCAM1 which is normally expressed by the vascular endothelium of the gastrointestinal tract. Also interacts with VCAM1 and fibronectin, an extracellular matrix component (Probable). It recognizes one or more domains within the alternatively spliced CS-1 region of fibronectin (Probable). Interactions involve the tripeptide L-D-T in MADCAM1, and L-D-V in fibronectin (Probable). Integrin ITGAE/ITGB7 (alpha-E/beta-7, HML-1) is a receptor for E-cadherin. (Microbial infection) Binds to HIV-1 gp120, thereby allowing the virus to enter GALT, which is thought to be the major trigger of AIDS disease. Interaction would involve a tripeptide L-D-I in HIV-1 gp120.
Tractability: Small molecule: a drug acting on it is in phase 2 or 3 trials; a structure with a bound ligand is known; a high-quality ligand is known; it belongs to a druggable protein family. Antibody: an approved drug acts on it; UniProt places it where antibodies can reach, with high confidence; its Gene Ontology location is reachable by antibodies, with high confidence; UniProt predicts a signal peptide or a membrane-spanning region; the Human Protein Atlas places it where antibodies can reach. PROTAC: ubiquitination databases record sites on it; its protein half-life has been measured.
Target class: Membrane receptor
Gene: Protein-coding gene on chromosome 12 (53,191,318 to 53,207,282, reverse strand). Ensembl gene ENSG00000139626.
Subcellular location: Cell membrane
Subcellular location (Human Protein Atlas): Cytosol; Plasma membrane
Pathways (Reactome):
Extracellular matrix organization: Integrin cell surface interactions
Immune System: Immunoregulatory interactions between a Lymphoid and a non-Lymphoid cell
Gene Ontology:
Molecular function: cell adhesion molecule binding; protein binding; integrin binding
Biological process: cell-matrix adhesion; cell-matrix adhesion involved in ameboidal cell migration; heterotypic cell-cell adhesion; integrin-mediated signaling pathway; leukocyte tethering or rolling; receptor clustering; substrate adhesion-dependent cell spreading; cell adhesion; cell adhesion mediated by integrin; cell-cell adhesion; immune response in gut-associated lymphoid tissue; leukocyte migration
Cellular component: cell surface; extracellular exosome; integrin alpha4-beta7 complex; integrin alphaE-beta7 complex; membrane; receptor complex; focal adhesion; integrin complex; plasma membrane
Genetic constraint (gnomAD): Loss-of-function variants: 57 observed, 83.28 expected, observed/expected ratio (o/e) 0.68, 90% interval 0.55 to 0.85. The upper end of that interval is the gene's LOEUF score, 0.85, which puts it in group 3 of 6, group 1 being the genes least tolerant of losing a copy. Missense variants: 917 observed, 1,056.9 expected, observed/expected ratio (o/e) 0.87, 90% interval 0.82 to 0.92. Synonymous variants: 453 observed, 425.82 expected, observed/expected ratio (o/e) 1.06, 90% interval 0.98 to 1.15.
Homologues: Orthologues: chimpanzee ITGB7 (99% identical), macaque ITGB7 (97% identical), pig ITGB7 (89% identical), rabbit ITGB7 (88% identical), dog ITGB7 (87% identical), rat Itgb7 (86% identical), mouse Itgb7 (86% identical), guinea pig ITGB7 (86% identical), tropical clawed frog itgb7 (51% identical), zebrafish itgb7 (42% identical), Drosophila melanogaster mys (37% identical), Caenorhabditis elegans pat-3 (37% identical). Paralogues in human: ITGB2 (45% identical), ITGB1 (43% identical), ITGB3 (38% identical), ITGB5 (38% identical), ITGB6 (36% identical), ITGB4 (33% identical), ITGB8 (28% identical), ITGBL1 (16% identical).
Diseases named in the same sentence as ITGB7 in open-access papers:
ITGB7 is named in the same sentence as 65 diseases in open-access papers, as found by Europe PMC text mining. Sharing a sentence is not in itself a finding about the gene and the disease. The quoted sentences say what the papers report.
multiple myeloma (13 papers, 2020 to 2026). "In contrast, in multiple myeloma (MM), oncogenic overexpression of ITGB7 in high-risk cases enhances interactions between malignant plasma B-cells and stromal cells, leading to cell-adhesion-mediated drug resistance." (PMID 41235257, 2025). "Oncogenic overexpression of integrin-β7 (ITGB7) in cases of high-risk multiple myeloma (MM) was reported to promote enhanced interactions between neoplastic plasma-B cells and stromal cells to develop cell-adhesion mediated drug resistance." (PMID 36737807, 2023). "ITGB7 is an integrin subunit, and previous studies have shown that elevated ITGB7 expression is closely related to the progression of multiple myeloma, pancreatic cancer, and intestinal inflammation." (PMID 41509664, 2026). "Previous studies have shown that ITGB7 is constitutively activated in multiple myeloma (MM) cells, and it has a remarkable anti-MM effect." (PMID 37644056, 2023). "ITGB7 is highly expressed in myeloma cells and tissues, it can regulate the biological processes of multiple myeloma cells such as adhesion, invasion, and migration, and patients with high expression of ITGB7 have a shorter survival time." (PMID 33335550, 2020). "Notably, SEs also contribute to therapeutic resistance, as seen in multiple myeloma, where SE-driven ITGB7 overexpression fosters cell-adhesion-mediated drug resistance." (PMID 41268574, 2025). "ITGB7 downregulation was reported to decrease adhesion and migration of multiple myeloma cells." (PMID 36059515, 2022). "ITGB7 is necessary for myeloma cell survival and CAM-DR, and has been shown to be constitutively active in myeloma cells." (PMID 33634031, 2020). "A method of cell-ECM adhesion is activation of integrins, and myeloma cells have shown preference toward very large antigen-4 (VLA-4) aka integrin α4ß1 and integrin ß7 (ITGB7)." (PMID 33634031, 2020). "Emphasizing the validity of this strategy, four of the top six targets by our ranking either already have FDA-approved therapeutics or are being clinically investigated in myeloma: BCMA (TNRFSF17 gene), TACI (TNFRSF13B), Integrin beta-7 (ITGB7), and CS-1/SLAMF7 (SLAMF7)." (PMID 35840578, 2022). "Notably, across these lines we detected almost all of the major immunotherapy targets in myeloma, as well as canonical flow cytometry markers for plasma cells: BCMA, CD138/SDC1, CD38, CD56, SLAMF7/CS-1, CD46, Integrin-b7 (ITGB7), CD74/HLA-DR, TACI, CD48/SLAMF2, and LY9/CD229." (PMID 35840578, 2022).
breast carcinoma (4 papers, 2023 to 2025). "For instance, a total of 200 eccDNA genes were obtained in breast cancer and among them, eccDNA-oriented ITGB7 was significantly upregulated in breast cancer patients and was associated with the menopause status of the patients." (PMID 38997648, 2024). "Most of these genes were associated with cancers of metabolic systems (DUSP6, SGK1, BMP4, RASGRF1, GDF15) followed by breast cancer (CACNA2D3, ITGB7), cancers of the central nervous system (PRKCA), or leukemia (MECOM, JAK3)." (PMID 36624125, 2023).
colorectal cancer (4 papers, 2022 to 2025). A primary or metastatic malignant neoplasm that affects the colon or rectum. "Previous mouse studies demonstrated a pivotal role of Itgb7 for intestinal T cell recruitment and correlated low levels of Itgb7 with colorectal cancer progression and maintenance of intestinal stem cells via Ecad-mediated interaction." (PMID 38386085, 2024). "Interestingly, ITGB7 was verified to suppress colorectal cancer pathogenesis by maintaining anti-tumor immunity, whereas it was predicted to evade anti-tumor immunity in OC which requires experimental evidence." (PMID 38814534, 2024). "We found a correlation of ITGB7 with expression of T cell markers and although the role of ITGB7 is poorly understood, increased levels of ITGB7+ leukocytes correlated with favored survival in a colorectal cancer mouse model due to blocking of tumorigenesis and progression." (PMID 36435874, 2022).
diabetes (3 papers, 2011 to 2022). "And ITGB7 (integrin subunit beta 7), is associated with Type 1 diabetes mellitus." (PMID 36088304, 2022). "Interestingly, diabetes-related alterations of the extracellular matrix and adhesion molecules were varied; Pecam, Mmp10, Lamc1, Itgb7, Mmp9, and Timp4 were up-regulated, but Col11a1, Fn1, Admts2, and Itgav were down-regulated." (PMID 21984919, 2011).
inflammatory bowel disease (3 papers, 2021 to 2026). A spectrum of small and large bowel inflammatory diseases of unknown etiology. "In addition, ITGB7 is important in T-cell homing in the gut and is involved in the pathogenesis of inflammatory bowel disease." (PMID 36059515, 2022). "While anterior gradient 2 and POF1B were also associated with inflammatory bowel disease or other noninfective gastroenteritis and colitis, CPA2 and ITGB7 were uniquely significantly associated with celiac disease." (PMID 41158112, 2026).
pancreatic cancer (3 papers, 2022 to 2026). "In pancreatic cancer (PC), ITGB7 was recently identified as a candidate gene associated with nab-paclitaxel resistance through whole-transcriptome sequencing in PC patient-derived organoids." (PMID 41235257, 2025). "In a previous study, TRIM2 was found to accelerate pancreatic cancer progression through the ROS-related NRF2/ITGB7/FAK axis, and excessive production of ROS has been considered to be the main mechanism of DMBA-mediated oral carcinogenesis." (PMID 36051486, 2022). "In a further mechanistic study, it was concluded that TRIM2 can accelerate the progression of pancreatic cancer through the ROS-related NRF2/ITGB7/FAK axis, which reveals a new regulatory role of TRIM2 through the regulation of redox homeostasis and integration of independent signaling pathways." (PMID 36051486, 2022).
colitis (2 papers, 2013 to 2026). Inflammation of the colon. "Thus, transfer of naive T cells from Itgb7−/− mice results in strongly delayed, although not complete prevention of colitis confirming the importance of the α4β7-dependent adhesion for rapid and efficient localization of T cells in intestinal tissues." (PMID 23630623, 2013).
COVID-19 (2 papers, 2021 to 2023). A disease caused by infection with severe acute respiratory syndrome coronavirus 2. "Additionally, we found that PCs in patients with severe COVID-19 had higher expression levels of inflammation genes (TNFSF10, S100A9, and S100A8) and chemokine-related genes (CCR2 and ITGB7) than those in patients with mild COVID-19." (PMID 33936072, 2021). "Increased expression of integrin β7 (ITGB7) was also observed on the circulating Tregs of patients with MIS-C, but not on those of pediatric patients with acute COVID-19, in agreement with a critical role of Notch1 in driving the expression of this marker." (PMID 36282598, 2023).
Crohn disease (2 papers, 2024 to 2025). A gastrointestinal disorder characterized by chronic inflammation involving all layers of the intestinal wall, noncaseating granulomas affecting the intestinal wall and regional lymph nodes, and transmural fibrosis. "In addition to inflammatory bowel diseases, such as Crohn’s disease and ulcerative colitis, ITGB7 plays a significant role in the pathogenesis of MM." (PMID 40597436, 2025). "Notably, FDA-approved monoclonal antibodies, such as etrolizumab, have been deployed to obstruct CD11a units and ITGB7 (integrin subunit beta 7) in inflammatory diseases such as severe plaque psoriasis, Crohn’s disease or ulcerative colitis, respectively." (PMID 39015503, 2024). "TRK-170, an ITGB7 inhibitor, is currently in Phase II clinical trial (NCT01345799) for moderate to severe Crohn’s disease." (PMID 40597436, 2025).
graft versus host disease (2 papers, 2023 to 2024). An immune system disorder that occurs after allogeneic hematopoietic stem cell transplant and is a reaction of donor immune cells against host tissues. "In addition to skin trafficking molecules, they expressed ITGA4 and ITGB7, encoding the integrin α4β7 which facilitates entry to the intestine, and were localised in gastrointestinal graft versus host disease (GVHD) lesions." (PMID 38817613, 2024).
liver cancer (2 papers, 2020 to 2022). An epithelial or non-epithelial malignant neoplasm that arises from the liver. "Immunofluorescence results showed that knockdown of ITGB4 and ITGB7 can up-regulated the expression of E-cadherin/catenin complex on membrane of liver cancer cells." (PMID 32127932, 2020). "Transwell assay results showed that Si-ITGB4-4204 weakened liver cancer cells motility significantly, but Si-ITGB7-5404 enhanced liver cancer cells motility evidently." (PMID 32127932, 2020). "Si-ITGB4-4204 weakened liver cancer cells motility significantly, but Si-ITGB7-5404 enhanced liver cancer cells motility evidently." (PMID 32127932, 2020). "Immunofluorescence test showed that silencing ITGB4 and ITGB7 can increase the membrane expression of α-cateninin, β-catenin and E-cadherin in liver cancer cells to some extent." (PMID 32127932, 2020). "To determine the exact role of ITGB4 and ITGB7 in development of liver cancer, we used Si-ITGB4-4204 and Si-ITGB4-5690 to knockdown ITGB4, and Si-ITGB7-5402 and Si-ITGB7-5404 to knockdown ITGB7 gene in Bel-7402." (PMID 32127932, 2020).
liver diseases (2 papers, 2020 to 2021). "Plenty of similarities between PSO and LP, along with the immunological mechanisms involved in the pathogenesis of both diseases and the association between PSO, LP, and IBD or liver disorders, inspired us to explore the potential diagnostic role of ITGB7 and MAdCAM-1 in these interrelationships." (PMID 34827121, 2021). "To assess if this infiltration of β7 positive T-cells was disease-specific, we analyzed the expression of ITGB7 in two other liver diseases." (PMID 32743534, 2020). "Apparently, in patients with LP, low RBC and HDL concentration may indirectly indicate low ITGB7 and increase the possibility of liver disorders." (PMID 34827121, 2021).
melanoma (2 papers, 2021 to 2022). A malignant, usually aggressive tumor composed of atypical, neoplastic melanocytes. "Primarily the differential methylation of a CpG island encompassing the region 53,197,471–53,197,983 within the ITGB7 (integrin subunit beta 7) gene was associated with survival of melanoma patients." (PMID 36435874, 2022). "There are only a few reports concerning ITGB7 expression in melanoma and its potential role." (PMID 34660316, 2021). "Hence, ITGB7 expression might serve as a prognostic marker in melanoma and potentially help to predict MBM progression states." (PMID 36435874, 2022).
ovarian carcinoma (2 papers, 2020 to 2024). A malignant neoplasm originating from the surface ovarian epithelium. "Among all analyzed integrin genes, we found increased ITGA3/A5/A10/A2B and ITGB3/B4/B8 expressions were significantly associated with poor OS, while decreased ITGA6/A7/AE and ITGB7 expression were significantly associated with poor OS in ovarian cancer patients." (PMID 32765584, 2020). "PDE10A and PTGS2 were significantly decreased, but ITGB7 was significantly increased in ovarian cancer." (PMID 38714753, 2024).
alcohol (1 paper, 2023). "We observe positive colocalization [posterior probability (PP) > 80%] for 5 of 18 proteins with the same traits (ADGRE2 and total cholesterol [TC]; ANGPTL7 and BMI, waist-hip ratio; ITGB7 and TC; NOMO1 and LDL, TC; SEMA3F and BMI, alcohol use), supporting the two-sample MR results." (PMID 37550624, 2023).
Anxiety (1 paper, 2019). Intense feelings of nervousness, tension, or panic often arise in response to interpersonal stresses. "The behavioral score of anxiety-like behavior of the adult males—but not females—yielded 5 significant correlations with Slc1a7, 9530052E02Rik, Itgb7, Tiam2, and Tspo (adjusted p = 0.048)." (PMID 30655507, 2019).
atopic dermatitis (1 paper, 2021). "Concentrations of soluble ITGB7 have not been studied in PSO or LP so far, but they have been investigated in children with atopic dermatitis (AD)." (PMID 34827121, 2021).
celiac disease (1 paper, 2026). An autoimmune genetic disorder with an unknown pattern of inheritance that primarily affects the digestive tract. "Prior studies highlight possible biological explanations behind the association of these proteins, CPA2 and ITGB7, with celiac disease." (PMID 41158112, 2026). "They identified a specific protein signature for celiac disease involving 20 proteins, three being the transglutaminase 2, ITGB7, and CPA2." (PMID 41158112, 2026). "Two of these proteins, CPA2 and ITGB7, were unique to celiac disease." (PMID 41158112, 2026). "Another proteomic study done on both plasma (30 individuals with CeD compared to 30 healthy controls) and duodenal tissue (19 individuals with CeD compared to 19 healthy controls) did not identify CPA2 or ITGB7 in the plasma of those with celiac disease." (PMID 41158112, 2026).
cervical cancer (1 paper, 2022). A primary or metastatic malignant neoplasm involving the cervix. "ITGB7 is involved in regulating adhesion and proliferation and glucose metabolism in cervical cancer." (PMID 35896848, 2022).
hepatocellular carcinoma (1 paper, 2022). A malignant tumor that arises from hepatocytes. "Chen’s research ITGB7 has a significant correlation with the tumor microenvironment of hepatocellular carcinoma, may represent new hepatocellular carcinoma ferroptosis inducing markers and have guiding significance for the treatment of hepatocellular carcinoma." (PMID 36482887, 2022).
HIV-1 infection (1 paper, 2019). The type species of lentivirus and the etiologic agent of acquired immunodeficiency syndrome (AIDS). "In addition, IRF7-induced genes important for cell trafficking (e.g., CXCL10 and ITGB7) may promote migration of effector cells to the mucosal sites where HIV-1 infection will occur." (PMID 30787294, 2019).
intestinal tumors (1 paper, 2024). "Recent studies have shown that ITGB7 plays a critical role in the recruitment of T cells to the intestine and that downregulation of ITGB7 is important in protecting intestinal tumors from attack by activated T cells." (PMID 38386085, 2024).
lichen planus (1 paper, 2021). A chronic, recurrent, pruritic inflammatory disorder of unknown etiology that affects the skin and mucus membranes. "MAdCAM-1 and ITGB7 molecules and their serum levels in patients with psoriasis and lichen planus have never been studied before; therefore, we are the first trying to analyze it in order to develop the current state of knowledge on psoriasis and lichen planus to better help patients." (PMID 34827121, 2021).
metastatic tumors (1 paper, 2024). "In line with previous observations, ITGB7 was expressed in primary and metastatic tumors (TCGA-SKCM) and like SUSD3 was associated with favored survival." (PMID 38386085, 2024).
ovarian tumor (1 paper, 2024). "GSE133859 provided paired OC samples, which demonstrated that ITGB3, ITGB4, ITGB7, and ITGB8 increased in ovarian tumor tissue compared with normal tissue." (PMID 38814534, 2024).
Stroke (1 paper, 2024). Sudden impairment of blood flow to a part of the brain due to occlusion or rupture of an artery to the brain. "Similarly, genes involved in integrin cell surface interactions including Itga10, Itgb3, Vcam1, Itgb1, Itgae, Itgb7, Itga1, Itga5, Icam1, Itgb2, Pecam1, and Icam2 were depleted in male MMP-3 KO stroke brains." (PMID 39000490, 2024).
virus infection (1 paper, 2022). "A study on Epstein–Barr virus (EBV) showed that virus infection induced the expression of ITGB7, which was beneficial for EBV infection." (PMID 36733771, 2022).